UCHL3 (ubiquitin C-terminal hydrolase L3)
Diseases named in the same sentence as UCHL3 in open-access papers (continued):
Sharing a sentence is not in itself a finding about the gene and the disease.
cancer (continued). "While UCHL3 has been identified as a novel mediator in DNA repair, aerobic glycolysis, and cancer progression, its role in bone formation has not been clarified." (PMID 36915132, 2023). "UCHL3, a member of the UCH subfamily of DUBs, has recently gained traction as a potential cancer target due to its effects on DNA repair pathways and upregulated expression in many cancers." (PMID 35053210, 2022). "Based on the lack of UCHL3 chemical probes with validated on-target activity in cells there is a clear need for an alternative strategy to elucidate UCHL3 activity in cancer." (PMID 35053210, 2022). "DUBs are critical key players in diverse processes such as (i) spermatogenesis (e.g. USP2, USP8, USP9y, USP14, USP26, Uchl-1, Uchl-3 and CYLD), (ii) cancer biology (e.g. USP7, USP10 and USP11), and (iii) stemness and differentiation (e.g. USP7, USP9x, USP22, USP44 and Psmd14)." (PMID 28659380, 2017). "Additionally, UCHL3 deubiquitinates and, therefore, stabilizes forkhead box M1 (FOXM1), a key transcription factor and regulator of cell cycle progression in pancreatic cancer leading to cancer progression." (PMID 35053210, 2022).
tumor (15 papers, 2020 to 2025). "For instance, UCHL3 is considered a hallmark of colon cancer in the blood, underscoring its significance in remodeling the tumor microenvironment." (PMID 39034372, 2024). "Uchl3-deficient mice were less prone to tumorigenesis and presented with a lower tumor burden." (PMID 37740194, 2023). "Our study further clarifies UCHL3’s multifaceted contribution to tumor progression, providing novel insights into its regulatory network." (PMID 41271634, 2025). "IHC analysis of tumor tissues from the mouse model revealed that UCHL3 expression in the TCID group remained unchanged." (PMID 41271634, 2025). "In xenografts constructed with HGC-27 cells, silencing UCHL3 resulted in reduced proliferation, along with smaller tumor size and weight." (PMID 41271634, 2025). "The results confirmed higher UCHL3 expression in tumor tissues, with significant positive correlations to TNM staging." (PMID 41271634, 2025). "The observation of the growth volume and weight of tumors in nude mice indicates that UCHL3 significantly promoted the tumor growth of HCC cells." (PMID 38965582, 2024). "To verify this funding, we stably expressed UCHL3 in OS-RC-2 and implanted 105 cells in mice dorsum, and separated tumor bulks after three weeks." (PMID 39034372, 2024). "We compared the expression of immune markers and UCHL3 in immune and tumor cells using a cell-type marker enrichment analysis." (PMID 39034372, 2024). "IHC analysis of the tumor in nude mouse tumors showed that UCHL3 overexpression increased EEF1A1 protein level, while UCHL3 inhibition downregulated EEF1A1 protein level." (PMID 38965582, 2024). "To validate the in vivo functionality of UCHL3, we conducted a subcutaneous tumor growth experiment using a nude mouse model." (PMID 38965582, 2024). "The outcome showed that UCHL3 ablation attenuated the pathological injury of tumor tissues and decreased the number of Ki67-positive cells (left)." (PMID 37740194, 2023). "All data validated an oncogenic action of UCHL3 during bladder carcinogenesis and tumor progression." (PMID 37740194, 2023). "Tumor growth was noted to be significantly impaired in mice inoculated with UCHL3-silenced H358 cells." (PMID 37830596, 2023). "The effect of Uchl3 knockout in vivo was also evaluated, and the results suggested it suppressed tumor growth." (PMID 37740194, 2023). "UCHL3 has been described as a tumor promoter that regulates DNA methylation, chromosome stability, and DNA repair in different types of malignancies." (PMID 37740194, 2023). "UCHL3-medicated tumor growth was significantly decreased by SOX12 knockdown, indicating the function of SOX12 in CRC." (PMID 37280524, 2023). "Further, we validated through qRT-PCR the elevated UCHL3 levels in NSCLC tissues (referred to as the Tumor group) compared with adjacent normal tissues (referred to as the Normal group)." (PMID 35918714, 2022). "Gain- and loss- of function assays were performed to assess the effects of LINC00665, UCHL3 and miR-582-5p on the in vitro cell malignant behaviors and immune escape as well as on the in vivo tumor growth." (PMID 35918714, 2022). "Mechanistically, through comprehensive biochemical screening and tumor samples profiling, we identified UCHL3 as a crucial deubiquitinase that binds explicitly to JAK2-phosphorylated BRD4 to maintain its stabilization." (PMID 34290255, 2021). "The mechanism by which UCHL3 promotes tumor stem-like properties through AhR requires further investigation." (PMID 32546741, 2020). "In summary, our findings revealed that AhR plays a critical role in maintaining the stem-like properties of cells overexpressing UCHL3, confirming that UCHL3 promotes tumor stem-like properties through stabilizing AhR." (PMID 32546741, 2020). "Compared with the injection of vector-transfected A549 cells, injection of UCHL3-overexpressing A549 cells significantly increased tumor size, volume, and weight after 1 month of growth, while the overall body weight was maintained." (PMID 32546741, 2020).
tumor (continued). "To further investigate the effect of UCHL3 on tumor formation in vivo, we performed a xenograft model experiment." (PMID 32546741, 2020). "The expression of UCHL3 expanded tumor sizes from about 30 mm2 to 500 mm2." (PMID 39034372, 2024). "In addition, recent studies have confirmed that UCHL3 stabilized YES associated protein (YAP) by deubiquitylation, and form a UCHL3/YAP positive feedback loop, thus promoting tumor progression." (PMID 39034372, 2024). "The remodeling of the tumor microenvironment may be one of the factors contributing to the promotion of RCC by UCHL3 and UCHL5." (PMID 39034372, 2024). "Finally, mice bearing xenografts derived from MES GSCs treated with joint UCHL3 depletion and IR displayed a lower rate of tumor formation and prolonged survival compared to those following IR treatment, and POLD4 overexpression inhibited this synergism." (PMID 38829550, 2024). "UCHL3 promoted tumor stem-like properties through stabilization of AhR." (PMID 37830596, 2023). "Therefore, LINC00665 can stabilize AhR protein through the LINC00665/miR-582-5p/UCHL3 regulatory axis, thus promoting the in vivo tumor formation of NSCLC cells and reducing the radiosensitivity." (PMID 35918714, 2022). "In ovarian cancer, UCHL3 deubiquitinates TRAF2 to facilitate tumor progression." (PMID 34016790, 2021). "Moreover, the combination of UCHL3 silencing and IR significantly decreased both tumor volume and tumor weight when compared to IR exposure alone." (PMID 34016790, 2021). "In this study, we showed that UCHL3 overexpression increased tumor stem-like properties." (PMID 32546741, 2020). "Finally, we determined that stemness-associated markers were significantly upregulated in xenograft tumor samples with UCHL3 protein knockdown compared with the control groups." (PMID 32546741, 2020). "Importantly, stable knockdown of UCHL3 suppressed tumor growth from H358 cells and inhibited tumor stem-like properties." (PMID 32546741, 2020). "Importantly, UCHL3 is reported to be negatively modulated by tumor suppressor microRNA." (PMID 37830596, 2023). "Notably, UCHL3 overexpression renders tumor cell resistance to chemotherapy in breast cancer." (PMID 34016790, 2021). "However, given the complexity of DDR regulation and tumor immune microenvironments, further studies are necessary to evaluate the therapeutic window, off-target effects, and optimal patient selection criteria before UCHL3-targeted strategies can be translated into clinical application." (PMID 40710178, 2025). "By downregulating UCHL3 expression in GC PDX models, we observed slower tumor growth, further confirming UCHL3’s therapeutic potential." (PMID 41271634, 2025). "Mechanistically, circMTA2 interacted with ubiquitin carboxyl-terminal hydrolase L3 (UCHL3) to restrain MTA2 ubiquitination and stabilize MTA2 protein expression, thereby facilitating tumor progression." (PMID 38474064, 2024). "Using immunohistochemical staining, we expanded the analysis of UCHL3 and POLD4 protein expression in GBM clinical tumor tissues, and a substantially positive correlation was presented." (PMID 38829550, 2024). "Tumor sphere formation assays and limiting dilution assays showed that POLD4 overexpression reversed the effects of UCHL3 on the sphere-forming ability and self-renewal capacity of MES GSCs." (PMID 38829550, 2024). "UCHL3 and EEF1A1 formed a functional axis in facilitating the malignant progression of HCC, proving new insights for the anti-tumor targeted therapy for HCC." (PMID 38965582, 2024). "Additionally, UCHL3 stabilizes the aryl hydrocarbon receptor (AHR) via deubiquitination, leading to increased PD-L1 expression and enhanced immune evasion in tumor cells." (PMID 40710178, 2025). "TCID attenuated UCHL3 activity without affecting its protein level and diminished tumor stem-like properties." (PMID 38829550, 2024). "UCHL3 and UCH37 are acknowledged oncogenes, while BAP1 is recognized as a tumor suppressor." (PMID 38965582, 2024).
tumor (continued). "Therefore, UCHL3 and EEF1A1 jointly promote the migration, stemness, and drug resistance of HCC cells, as well as influencing the growth of mouse tumor models." (PMID 38965582, 2024). "Nevertheless, our results suggest that WT UCHL3, but not UCHL3 mutants, promotes tumor growth and stem-like properties through stabilizing AhR in a DUB activity-dependent manner." (PMID 32546741, 2020). "Thus, we confirm that UCHL3 is a deubiquitinase for JAK2-phosphorylated BRD4, whose overexpression in CRC may provide a mechanism to maintain the BRD4 protein abundance in an inflammatory tumor microenvironment." (PMID 34290255, 2021).
infection (2 papers, 2015 to 2025). The state of being infected such as from the introduction of a foreign agent such as serum, vaccine, antigenic substance or organism. "First data in a proteome analysis from S. aureus infected macrophage-like cell line THP1 showed a decrease in the abundance of the analyzed proteins USP7, USP48, UCHL3, OTUD7B, and SENP1 (data not shown) which might indicate an intracellular role of Spls during infection." (PMID 39985644, 2025).
neurological disorders (2 papers, 2018 to 2025). "Thus, we conclude that UCHL3 is a player in PDB repair and its level is downregulated in at least two PDB repair-deficient human neurological disorders." (PMID 29898404, 2018).
UCHL3 also shares sentences with these, for which no sentence is quoted: hepatocellular carcinoma (2 papers); thyroid cancer (2); cervical squamous cell carcinoma (1); cognitive decline (1); diabetic retinopathy (1); Hyperglycemia (1); kidney cancer (1); male infertility (1); Obesity (1); ovarian tumor (1); pulmonary fibrosis (1); retinal degeneration (1); Salmonella Infections (1); spinocerebellar ataxia with (1).